MAL (mal, T cell differentiation protein (MAL blood group))
Diseases named in the same sentence as MAL in open-access papers (continued):
Sharing a sentence is not in itself a finding about the gene and the disease.
cancer (continued). "ROC curve analyses further confirmed the superior performance of the combined CADM1/MAL methylation panel in detecting carcinoma (AUC = 0.912), compared to CADM1 and MAL alone (both AUC = 0.770) and PAX1 (AUC = 0.813)." (PMID 40564169, 2025). "In clinician-collected cervical samples, DNA methylation of MAL and miR124-2 was significantly higher in HSIL/cancer compared with normal/LSIL samples while the methylation of CADM1 failed to distinguish between cytology grades." (PMID 38904134, 2024). "MAL (LUAD, THYM, and UCEC), MAL2 (BRCA, PAAD, and UCEC), and PLLP (KICH, KIRC, and UCEC) present strong correlations (p ≤ 0.001) in three types of cancer, and MALL (KIRC and PAAD), CMTM8 (KIRC and KIRP), and MYADM (LUSC and THYM) do so in two cancer types." (PMID 37345137, 2023). "Completed: cfDNA methylatation (RASSF1A, MAL and SFRP1) is a phenotypic feature of BC, and can be used for cancer diagnosis." (PMID 36430675, 2022). "The novel family member of MAL proteolipid, MAL2, is known to bind with tumor protein D52, thus participating in regulating the tumorigenicity of multiple human cancer types." (PMID 33634966, 2021). "In view of making use of MAL and VILL for the treatment of metastasis of these types of cancer, one can use small molecules to enhance MAL gene expression or function and/or to attenuate VILL gene expression or function." (PMID 33672337, 2021). "Compared to normal cytology with histology ≤ LSIL, the methylation levels of CADM1 and MAL increased 5.3 and 6.2 folds in CINII/III, and 143.5 and 454.9 folds in carcinomas, respectively." (PMID 30608989, 2019). "Univariate analyses showed that serum methylation levels of MAL and SST were significantly predictive of cancer-specific death." (PMID 28187169, 2017). "Here, we designed and analyzed a multiplex qMSP assay for three genes whose methylation was previously found to be informative for cervical (pre)cancer (i.e. CADM1, MAL and hsa-miR-124-2) as well as a reference gene β-actin." (PMID 23176198, 2012). "Our results show that exogenous expression of MAL in HNSCC cell lines inhibited the proliferation, invasion, and induced apoptosis of cancer cells in vitro and tumorigenicity in vivo." (PMID 21092172, 2010). "MAL proteolipid family (MALs), including T‐cell differentiation protein (MAL), T‐cell differentiation protein 2 (MAL2), and T‐cell differentiation protein like (MALL), were involved in the progression and prognosis of many different cancers." (PMID 40625454, 2024). "Using pharmacological inhibitors to analyze the proliferation, metastasis and invasion of cancer cells and the expression of EMT-related markers, we further showed that MAL inhibited the proliferation, metastasis and invasion of GC cells and interfered with the EMT by inhibiting STAT3." (PMID 35093120, 2022). "Like MAL, VILL gene expression also has a prognostic value, and an increase in MAL gene expression and/or a decrease in VILL gene expression may confer survival advantages in several types of cancer." (PMID 33672337, 2021). "Inactivating hypermethylation of the MAL promoter might be prevalent also in other cancer types where low expression of MAL has been shown not to correlate with allelic loss or somatic mutations in the MAL gene." (PMID 18346269, 2008). "Hypermethylation of genes such as ADAMTS1 and MAL are also suitable biomarkers for early detection, as they are infrequently methylated in normal mucosa taken from individuals without cancer (0% and 5%, respectively), but highly methylated in malignant lesions (71% and 82%, respectively)." (PMID 19117505, 2008). "The promoters of ADAMTS1, MAL, and MGMT were frequently methylated in benign samples as well as in malignant tumors, independent of microsatellite instability." (PMID 19117505, 2008).
cancer (continued). "MAL and PCDH17 CpG-rich regions have never been functionally characterised in humans or canines, and, to the best of the authors’ knowledge, the only available data concern the localisation and methylation profile of specific CpGIs in human cancers." (PMID 35409379, 2022). "From a clinical point of view, IL1RN, MAL and TGM3 were not clearly identified as potential HNSCC markers, while few data have been published concerning the implication of FN1, KRT, MMP1, PLAU and SPARC in this type of cancer." (PMID 19835631, 2009).
infection (12 papers, 2011 to 2022). The state of being infected such as from the introduction of a foreign agent such as serum, vaccine, antigenic substance or organism. "As expected through this example, loss of function in MAL decreases the inflammatory response which leads to susceptibility to the infection." (PMID 33072109, 2020). "Surprisingly only EPEC caused a significant change in MAL-GFP localization under the infection conditions tested." (PMID 21490959, 2011). "It is of interest to investigate if other pathogens are also able to physically modulate MAL signaling to determine whether its deficiency could interfere with the progression of infection." (PMID 33072109, 2020). "Recent studies have shown that the combination of methylation-mediated silencing of CADM1 (cell adhesion molecule 1) and MAL (T-lymphocyte maturation-associated protein) promoter genes in cervical scrapes seems to be related to the duration of hrHPV infection and the severity of the SIL/CIN lesion." (PMID 31067838, 2019). "However, in some combinations with MAL, MyD88 has an effect on the risk of infection." (PMID 33072109, 2020). "Thus, methylation analyses of CADM1, MAL, and miR124 seem to be able to distinguish hrHPV-positive patients with transforming lesions at short-term risk of progression from women with clinically irrelevant infections." (PMID 31067838, 2019). "Disruption of the MAL cluster in B. thailandensis reduced lethality following infection of C. elegans, and purified malleilactone was toxic to mammalian cells at micromolar concentrations." (PMID 25085508, 2014). "Infection of SRF-knockdown cells with EPEC resulted in a significant reduction in nuclear accumulation of MAL-GFP to 13.39%±1.61% compared to infection of wild type or non-targeting siRNA transfected COS-7 cells 45.38%±5.5% and 39.04%±5.39% respectively." (PMID 21490959, 2011). "68.2%±6.17% of cells expressing TirMC displayed a nuclear localization of MAL-GFP after 5 hours of infection with EPEC Δtir." (PMID 21490959, 2011). "In contrast, nuclear localization of MAL-GFP was significantly reduced to 27.9%±4.03% (p = 0.000225) in cells expressing TirMC (Y474F) following infection with EPEC Δtir." (PMID 21490959, 2011). "In addition, as functional studies showed, the depletion of MAL led to a significant decrease in infection, with a drastic reduction in the number of lytic plaques in MAL-silenced cells." (PMID 32521696, 2020). "Indeed, PumA was translocated into host cells during infection to directly interact with MAL at the plasma membrane controlling TLR signaling." (PMID 33072109, 2020). "Importantly, the depletion of MAL led to a significant decrease in infection, with a drastic reduction in the number of lytic plaques in MAL-silenced cells." (PMID 31748392, 2020). "The trafficking of virions associated with MAL-positive vesicles toward a noninfected cell appears to spread infection to the adjacent cell." (PMID 31748392, 2020). "How the function of MAL fits within an overall regulatory framework that promotes virulence is not clear, although it is conceivable that BsaN-mediated suppression of MAL reduces the production of toxic products during infection, thereby promoting long term survival within eukaryotic hosts." (PMID 25085508, 2014). "To test the hypothesis that EPEC-induced nuclear accumulation of MAL is driven by infection-driven changes in G∶F-actin ratios within the host cell, we quantified the G- and F-actin in EPEC infected cells relative to uninfected cells." (PMID 21490959, 2011). "Regardless of MAL, polymorphism in MyD88 alone did not influence the infection." (PMID 33072109, 2020). "Furthermore, co-morbidities such as diabetes are known to increase the amount of RAGE ligands, which could influence MAL functions during infection." (PMID 33072109, 2020). "To confirm that MAL functions as a coactivator of SRF during EPEC infection we measured the expression levels of known SRF target genes at 3, 5 and 8 hours post infection." (PMID 21490959, 2011).
infection (continued). "Infection of epithelial cells with EPEC Δtir does not induce MAL-GFP nuclear accumulation, but this phenotype is rescued by the exogenous expression of Tir." (PMID 21490959, 2011).
infectious disease (1 paper, 2020). A disorder directly resulting from the presence and activity of a microbial, viral, or parasitic agent in humans. "Effect of MAL deficiency during infectious and non-infectious diseases." (PMID 33072109, 2020). "Over the last decade, a large number of clinical and experimental studies focused on the role of MAL in the control of infectious and non-infectious diseases." (PMID 33072109, 2020).
MAL also shares sentences with these, for which no sentence is quoted: renal carcinoma (3 papers); adenocarcinoma (2); breast invasive carcinoma (2); colitis (2); hepatocellular carcinoma (2); non-small cell lung carcinoma (2); pancreatic cancer (2); renal cell carcinoma (2); anal disease (1); bacterial infection (1); benign colorectal tumours (1); benign tumours (1); bladder urothelial carcinoma (1); bowel cancer (1); breast tumors (1); C. perfringens infection (1); cardiac hypertrophy (1); cervical squamous cell carcinoma (1); cholangiocarcinoma (1); chronic myeloid leukemia (1); clear cell carcinoma (1); colorectal adenocarcinoma (1); cutaneous T-cell lymphoma (1); diffuse large B-cell lymphoma (1); emphysema (1); endometrial cancer (1); glioma (1); head and neck cancer (1); Hematuria (1); intrauterine growth restriction (1).
A further 16 diseases each share a sentence with MAL in 1 paper.